AP4M1 (adaptor related protein complex 4 subunit mu 1)
Description:
Component of the adaptor protein complex 4 (AP-4). Adaptor protein complexes are vesicle coat components involved both in vesicle formation and cargo selection. They control the vesicular transport of proteins in different trafficking pathways. AP-4 forms a non clathrin-associated coat on vesicles departing the trans-Golgi network (TGN) and may be involved in the targeting of proteins from the trans-Golgi network (TGN) to the endosomal-lysosomal system. It is also involved in protein sorting to the basolateral membrane in epithelial cells and the proper asymmetric localization of somatodendritic proteins in neurons (By similarity). Within AP-4, the mu-type subunit AP4M1 is directly involved in the recognition and binding of tyrosine-based sorting signals found in the cytoplasmic part of cargos. The adaptor protein complex 4 (AP-4) may also recognize other types of sorting signal (By similarity).
Synonyms: mu-ARP2; MU-4; SPG50; CPSQ3
Tractability: Antibody: UniProt places it where antibodies can reach, with high confidence. PROTAC: ubiquitination databases record sites on it.
Gene: Protein-coding gene on chromosome 7 (100,100,841 to 100,110,345, forward strand). Ensembl gene ENSG00000221838.
Subcellular location: Golgi apparatus, trans-Golgi network membrane; Early endosome
Pathways (Reactome):
Vesicle-mediated transport: Lysosome Vesicle Biogenesis
Gene Ontology:
Molecular function: protein binding; protein domain specific binding; clathrin adaptor activity; protein transmembrane transporter activity
Biological process: autophagosome assembly; Golgi to endosome transport; Golgi to lysosome transport; intracellular protein transport; protein targeting; protein targeting to lysosome; intracellular protein localization; post-Golgi vesicle-mediated transport; protein localization to basolateral plasma membrane; vesicle-mediated transport; protein transmembrane transport
Cellular component: AP-4 adaptor complex; early endosome; extracellular exosome; trans-Golgi network; endosome lumen; trans-Golgi network membrane; clathrin adaptor complex; cytosol; Golgi apparatus
Genetic constraint (gnomAD): Loss-of-function variants: 58 observed, 65.25 expected, observed/expected ratio (o/e) 0.89, 90% interval 0.72 to 1.11. The upper end of that interval is the gene's LOEUF score, 1.11, which puts it in group 4 of 6, group 1 being the genes least tolerant of losing a copy. Missense variants: 626 observed, 613.45 expected, observed/expected ratio (o/e) 1.02, 90% interval 0.95 to 1.09. Synonymous variants: 290 observed, 252.85 expected, observed/expected ratio (o/e) 1.15, 90% interval 1.04 to 1.26.
Gene-disease validity (ClinGen):
ClinGen rates the evidence that AP4M1 causes each of these diseases.
AP-4 deficiency syndrome (autosomal recessive): Definitive. A genetic disorder associated with variation(s) in the AP4 genes: AP4B1, AP4E1, AP4M1, and AP4S1.
Homologues: Orthologues: chimpanzee AP4M1 (99% identical), macaque AP4M1 (99% identical), pig AP4M1 (96% identical), dog AP4M1 (95% identical), rabbit AP4M1 (95% identical), guinea pig AP4M1 (93% identical), mouse Ap4m1 (93% identical), rat Ap4m1 (93% identical), tropical clawed frog ap4m1 (60% identical), zebrafish ap4m1 (60% identical). Paralogues in human: AP1M2 (28% identical), AP1M1 (27% identical), AP2M1 (25% identical), STON1 (20% identical), AP3M1 (19% identical), AP3M2 (18% identical), STON2 (18% identical).
Diseases named in the same sentence as AP4M1 in open-access papers:
AP4M1 is named in the same sentence as 46 diseases in open-access papers, as found by Europe PMC text mining. Sharing a sentence is not in itself a finding about the gene and the disease. The quoted sentences say what the papers report.
Intellectual disability (9 papers, 2013 to 2023). "Variants in AP4M1 are related to spastic paraplegia, intellectual disability, hearing loss, and microcephaly." (PMID 38254912, 2023). "We used whole-exome sequencing and identified a novel and truncating AP4M1 mutation in two brothers with cerebral palsy and intellectual disability." (PMID 25496299, 2014). "This study shows an AP4M1 mutation associated with aggressive behavior in addition to mild dysmorphic features, intellectual disability, spastic paraparesis and reduced head circumference." (PMID 25496299, 2014). "Exome sequencing in three patients with severe intellectual disability, microcephaly, epilepsy, dystonia, spasticity and cerebral atrophy revealed the same homozygous substitution p.Arg338* in AP4M1." (PMID 36371792, 2023). "For instance, most subtypes of CP that involve mental retardation are induced by recessive variations in the genes of 4 protein-binding complexes (AP4M1, AP4E1, AP4S1, and AP4B1)." (PMID 36323241, 2023). "Homozygous mutations in AP4M1, located in the region including PILRA and STAG3, cause spastic tetraplegia, intellectual disability, and white matter loss." (PMID 30108311, 2020). "A subset of these genes has been implicated in other neurobehavioral disorders including depression (SLIT3), epilepsy (CLCN2, PRICKLE1), intellectual disability (AP4M1), schizophrenia (WDR60), and Tourette syndrome (OFCC1)." (PMID 24410847, 2014).
Spastic paraplegia (9 papers, 2013 to 2026). Complete loss of the ability to move the lower limbs accompanied by spasticity of the lower limbs. "For instance, two patients harboring biallelic AP4M1 pathogenic variants exemplified the classical phenotype of AP‐4 adaptinopathy, with early‐onset spastic paraplegia, ventriculomegaly, and corpus callosum thinning." (PMID 41466769, 2026). "A 2‐year‐old female patient with spastic paraplegia and developmental delay was diagnosed with an AP4M1‐related adaptinopathy based on a homozygous c.1012C>T (p.Arg338*) variant." (PMID 41466769, 2026). "Namely, AP4M1 (SPG50) is involved in autosomal recessive spastic paraplegia 50 (MIM#612936)." (PMID 36371792, 2023). "It follows that four types of AP‐4‐associated spastic paraplegia do exist, all of them with autosomal recessive inheritance pattern: spastic paraplegia 47 (SPG47)/AP4B1, spastic paraplegia 50 (SPG50)/AP4M1, spastic paraplegia 51 (SPG51)/AP4E1, and spastic paraplegia 52 (SPG52)/AP4S1." (PMID 39723768, 2025). "After that, 3 cases of spastic paraplegia were found in patients (No. 2, 22, and 26) with responsible genes including (HACE1, ATL1, AP4M1), respectively, and two cases of cerebellar ataxia in patients (No. 14 and 43), whose responsible genes were SNX14, TDP2, respectively." (PMID 34540776, 2021).
microcephaly (7 papers, 2013 to 2025). A congenital or acquired developmental disorder in which the circumference of the head is smaller than normal for the person's age and sex. "We here report on a patient with an AP4M1 mutation, short stature, and severe, congenital microcephaly that initially mimicked MCPH." (PMID 28464862, 2017). "In individuals with diseases previously related to the TAF6 and AP4M1 genes, some of the clinical features observed include reduced growth, including microcephaly." (PMID 38254912, 2023). "Short stature and severe congenital microcephaly have however not been reported with AP4M1 mutation." (PMID 28464862, 2017). "The AP4M1 defect shares these features with the defects of the other components of the heterotetrameric AP4 complex, namely AP4B1, E1 and S1, which have further been associated with short stature and, inconsistently, with microcephaly." (PMID 28464862, 2017). "Our findings expand the AP4M1 phenotype to severe microcephaly of prenatal onset, and more generally suggest that the AP4 defect might share mechanisms of prenatal neuronal depletion with other genetic defects of brain development causing congenital, primary microcephaly." (PMID 28464862, 2017).
hereditary spastic paraplegia (5 papers, 2017 to 2025). Hereditary spastic paraplegias (HSP) comprise a genetically and clinically heterogeneous group of neurodegenerative disorders characterized by progressive spasticity and hyperreflexia of the lower limbs. "Autosomal recessive hereditary spastic paraplegia (HSP) due to AP4M1 mutations is a very rare neurodevelopmental disorder reported for only a few patients." (PMID 29096665, 2017). "Indeed, mutations in genes encoding all subunits of AP-4 (ε1; AP4E1, β1; AP4B1, μ1; AP4M1 and σ1; AP4S1) have been identified as leading to a complex form of hereditary spastic paraplegia (HSP) termed AP-4 deficiency syndrome (henceforth AP-4 deficiency)." (PMID 31142229, 2020).
developmental delay (3 papers, 2017 to 2026). "A 1‐year‐old male patient with recurrent febrile seizures and developmental delay was diagnosed with an AP4M1‐related adaptinopathy due to a homozygous c.929 + 1G>T splice site variant." (PMID 41466769, 2026).
schizophrenia (3 papers, 2011 to 2025). A major psychotic disorder characterized by abnormalities in the perception or expression of reality. "AP4M1, which encodes a subunit of AP-4 complex responsible for transportation of proteins from Golgi, was abnormally expressed in schizophrenia and bipolar disorder." (PMID 22373040, 2011).
Cognitive impairment (2 papers, 2023 to 2025). Abnormal cognition is characterized by deficits in thinking, reasoning, or remembering. "The association with cognitive impairment occurred only in case of concomitant presence of variants in the AP4M1 gene (c.1117C>T; stop codon) and the SGCE gene (c.232+1G>T; splicing mutation), which were detected in one male and one female patient." (PMID 38137339, 2023).
developmental disabilities (1 paper, 2017). "Copy number variants (CNVs) involving the AP4M1 gene have also been implicated in developmental disabilities or congenital anomalies." (PMID 29096665, 2017).
giant axonal neuropathy (1 paper, 2023). A rare inherited disorder affecting the neurofilaments. "In this study, utilizing an approach similar to that used in our prior work on giant axonal neuropathy and CLN7 gene therapies, we evaluated the efficacy and safety of AP4M1 gene transfer in vitro in fibroblasts from patients with SPG50 and in vivo in Ap4m1-KO mice." (PMID 36951961, 2023).
hepatocellular adenoma (1 paper, 2023). A benign epithelial neoplasm arising from the hepatocytes. "Taken together, i.t.-administered AAV9/AP4M1 doses up to 5 × 1011 vg/mouse were overall well tolerated in WT mice, with infrequent occurrence of hepatocellular adenomas." (PMID 36951961, 2023).
hepatocellular carcinoma (1 paper, 2023). A malignant tumor that arises from hepatocytes. "The expression level of AP4M1 in cancers was investigated by The Cancer Genome Atlas (TCGA) and Gene Expression Omnibus (GEO) databases, and the correlation between AP4M1 and hepatocellular carcinoma (HCC) clinicopathological parameters were analyzed." (PMID 37821948, 2023). "We further analyzed the prognostic impact of AP4M1 on patients with hepatocellular carcinoma." (PMID 37821948, 2023). "In addition, AP4M1 can be used for the prediction of immune cell infiltration and immune phenotype in hepatocellular carcinoma and positively correlates with various immune checkpoint-related genes, which laid a foundation for future new immunotherapies for HCC." (PMID 37821948, 2023).
Hydrocephalus (1 paper, 2025). Hydrocephalus is an active distension of the ventricular system of the brain resulting from inadequate passage of CSF from its point of production within the cerebral ventricles to its point of absorption into the systemic circulation. "More patients have mild ventricular enlargement caused by non‐hydrocephalus causes, e.g. SPG47/AP4B1, SPG50/AP4M1, SPG51/AP4E1." (PMID 39932116, 2025).
liver cancer (1 paper, 2023). An epithelial or non-epithelial malignant neoplasm that arises from the liver. "We also explored that the mRNA expression levels of AP4M1 in liver cancer patients at AFP > 400 were significantly higher than in the AFP ≤ 400ng/ml group." (PMID 37821948, 2023).
lysosomal disorders (1 paper, 2022). "In fact, isolated cases with GP hypointensities consistent with iron excess are known in at least 17 distinct genes, including AP4M1 and AP4S1, which, like FUCA1, GLB1, and TPP1, are involved in lysosomal disorders." (PMID 36233161, 2022).
morbid obesity (1 paper, 2015). An excess of body weight, normally defined as an individual with a body mass index greater than 35 or a body weight greater than one hundred percent of ideal body weight. "Altogether, our results suggest that the phenotype observed in our patients results from the additional effects of AP4M1 and AZGP1 mutations accounting for the neurological signs on one hand and the precocious morbid obesity on the other hand." (PMID 26029708, 2015). "We propose that the siblings' phenotype results from the combined effects of mutations in both AP4M1 and AZGP1 that account for the neurological signs and the morbid obesity of early onset, respectively." (PMID 26029708, 2015).
pneumonia (1 paper, 2013). An acute, acute and chronic, or chronic inflammation focally or diffusely affecting the lung parenchyma, caused by an infection in one or both of the lungs (by bacteria, viruses, fungi, or mycoplasma.). "Nonetheless, one patient with an AP4M1 mutation died from pneumonia at a very young age, although the causal pathogen was not clearly identified." (PMID 23472171, 2013).
polymicrogyria (1 paper, 2023). A developmental brain abnormality characterized by an excessive amount of small convolutions on the surface of the brain and cognitive dysfunction.
shigellosis (1 paper, 2023). Shigellosis is a bacterial infection leading to dysentery and is caused by Shigella, which are small, ubiquitous Gram-negative bacteria belonging to the enterobacteria family. "KEGG enrichment results suggested that AP4M1 and co-expressed genes were mainly involved in the Ribosome, Spliceosome, RNA transport, Shigellosis, Ribosome biogenesis in eukaryotes, Synaptic vesicle cycle, Proteasome, Cell cycle, Pyrimidine metabolism, Mismatch repair." (PMID 37821948, 2023).
cancer (2 papers, 2019 to 2023). A tumor composed of atypical neoplastic, often pleomorphic cells that invade other tissues. "AP4M1 is a protein-coding gene that plays a crucial role in transporter activity, recognition, and hereditary-associated diseases, but it’s largely unknown in cancers." (PMID 37821948, 2023). "By evaluating the expression of AP4M1 in each type of cancer in the TCGA database, we discovered that the levels of AP4M1 mRNA are significantly elevated in HCC." (PMID 37821948, 2023). "We found that the high expression of AP4M1 was related to the inferior prognosis and cancer-immune regulation in HCC." (PMID 37821948, 2023). "AP4M1 is closely related to cancer-immune regulation and could be a novel target for HCC, and guiding new strategies for the diagnosis and treatment of HCC patients." (PMID 37821948, 2023). "By exploring the correlation between AP4M1 gene and clinical features, it was found that the overexpression of AP4M1 was significantly correlated with various clinical features, and a trend toward increased AP4M1 expression with advanced cancer stages (T3 and T4) and grades (G3 and G4)." (PMID 37821948, 2023). "Taken together, our study suggests that AP4M1 may be involved in the malignant progression of HCC, as well as the cancer immune regulation, which provides new insights for the diagnosis and treatment of HCC." (PMID 37821948, 2023). "Furthermore, we analyzed the AP4M1 protein levels from the Pan-cancer proteomics study and CPTAC database, and the results were in line with our finding that the AP4M1 protein levels were increased in HCC." (PMID 37821948, 2023). "At present, there is no relevant studies report on AP4M1 in cancers." (PMID 37821948, 2023).
neurodegenerative disease (1 paper, 2023). A disorder of the central nervous system characterized by gradual and progressive loss of neural tissue and neurologic function. "Spastic paraplegia 50 (SPG50) is a rare neurodegenerative disease caused by loss-of-function mutations in AP4M1." (PMID 37183815, 2023).
neurological disorder (1 paper, 2023). "Spastic paraplegia 50 (SPG50) is an ultrarare childhood-onset neurological disorder caused by biallelic loss-of-function variants in the AP4M1 gene." (PMID 36951961, 2023).
tumor (1 paper, 2023). "Univariate Cox analysis indicated that AP4M1 (HR = 1.732, p = 0.002), tumor status (HR = 2.317, p < 0.001), pathologic stage (HR = 2.504, p < 0.001) and pathologic T stage (HR = 2.598, p < 0.001) were associated with patients’ OS." (PMID 37821948, 2023). "Although our observation was preliminary and no study reported the exact effect of AP4M1 in immune-related processes, we revealed a possible role of AP4M1 in tumor immune microenvironment, which was proposed to be an in-depth exploration for future investigation." (PMID 37821948, 2023). "Subsequently, HCC samples were divided into AP4M1-high and AP4M1-low expression groups, and we sought to determine whether various expression groups of AP4M1 differ in the HCC tumor immune microenvironment." (PMID 37821948, 2023).
AP4M1 also shares sentences with these, for which no sentence is quoted: depression (3 papers); epilepsy (3); Ataxia (2); bipolar disorder (2); spastic (2); autism (1); cerebellar ataxia (1); Cerebral atrophy (1); cerebral palsy (1); CLN7 disease (1); developmental and epileptic encephalopathy (1); Dystonia (1); febrile seizures (1); hearing loss (1); infection (1); lymph node metastasis (1); Macrocephaly (1); movement disorder (1); neurodevelopmental disorder (1); psychosis (1); Spastic paraparesis (1); Spastic tetraplegia (1); tetraplegia (1); Tourette syndrome (1).